BACE1 (beta-secretase 1)
Diseases named in the same sentence as BACE1 in open-access papers (continued):
Sharing a sentence is not in itself a finding about the gene and the disease.
Alzheimer disease (continued). "In this work, protein-protein interaction analysis was conducted based upon the genes from a clinical database to identify the top protein targets with most data-indicated involvement in Alzheimer’s disease, which include ABCA1, CYP46A1, BACE1, TREM2, GSK3B, and SREBP2." (PMID 37444065, 2023). "Beta secretase 1 (BACE1, A01.004) is a membrane-anchored pepsin-like aspartic protease, which prefers hydrophobic recognition stretches and cleaves the amyloid precursor protein (APP) as a critical step in the development of Alzheimer’s disease." (PMID 37762340, 2023). "The NLRP3, BACE1, AChE, and GSK-3β are closely related to Alzheimer’s disease." (PMID 35991454, 2022). "BACE1 and BACE2 β-secretases have been widely investigated in the context of Alzheimer’s disease." (PMID 35884586, 2022). "Inhibitory activities against the key enzymes relevant to obesity (lipase), diabetes (α-glucosidase and α-amylase), and Alzheimer’s disease (AChE, BChE, and BACE-1) and the nonenzymatic glycation reaction were also assessed." (PMID 35161275, 2022). "Compounds 1 and 25 moderately prohibited BACE1 (β-secretase 1), an enzyme involved in Alzheimer’s disease pathogenesis, however, the other metabolites had no or weak activity." (PMID 35447894, 2022). "The aim of this study was to compare an antibody-based PET ligand targeting nonfibrillar Aβ with 11C-PiB after β-secretase (BACE-1) inhibition in 2 Alzheimer disease mouse models at an advanced stage of Aβ pathology." (PMID 34088777, 2022). "Since there are no effective therapeutic drugs in the clinic, the study of BACE1 inhibitors for therapeutic intervention in patients with Alzheimer's disease has increasingly become a research hotspot." (PMID 34134572, 2021). "Using kinetics and molecular docking studies, it was shown that both 6-FUmb and 8-FUmb possessed an anti-Alzheimer’s disease activity via noncompetitive inhibition of BACE1 in vitro, and the activity of 6-FUmb was more pronounced." (PMID 34946562, 2021). "Beta-site amyloid precursor protein cleaving enzyme 1 (BACE1) inhibitors, promising drugs in treatment of Alzheimer’s disease (not introduced yet), were modified in this way in order to improve blood–brain permeability due to increased lipophilicity." (PMID 34502040, 2021). "BACE inhibitors, which decrease BACE1 (β-secretase) cleavage of the amyloid precursor protein (APP) and subsequently reduce neurotoxic amyloid-β (Aβ) levels, have been in clinical trials for the treatment of Alzheimer’s disease." (PMID 34302009, 2021). "Another interesting observation is that a significantly decreased expression of miR-19b-3p has been reported to coincide with increased protein expression of BACE1 in Alzheimer’s disease, although miR-19b-3p does not directly target BACE1." (PMID 29293623, 2018). "In the context of Alzheimer’s disease, lentivirus vectors have been applied for RNA silencing to knock down BACE1 attenuated amyloid precursor protein (APP) cleavage and β-amyloid production, resulting in reduced neurodegeneration and behavioral deficits in an Alzheimer’s disease mouse model." (PMID 29883422, 2018). "We investigated the anti-Alzheimer disease (anti-AD) potential of these coumarins by assessing their ability to inhibit acetylcholinesterase (AChE), butyrylcholinesterase (BChE), and β-site amyloid precursor protein (APP) cleaving enzyme 1 (BACE1)." (PMID 28946641, 2017). "In this work, we focused on knowledge cliffs next to some of the most-established interactions such as BACE1-APP and found four “potential new candidates”, namely TP53INP2, RTN4, F2RL3, and FBXO2, presumably new targets for Alzheimer’s disease as guided by the knowledge cliff concept." (PMID 26346705, 2015). "Although BACE1 is a major therapeutic target for Alzheimer’s disease (AD), potential side effects of BACE1 inhibition are not well characterized." (PMID 24405708, 2014).
Alzheimer disease (continued). "Amyloid precursor protein cleaving enzyme 1 (BACE1), an aspartyl protease, initiates processing of the amyloid precursor protein (APP) into β-amyloid (Aβ); the peptide likely contributes to development of Alzheimer’s disease (AD)." (PMID 23133641, 2012). "FA-induced decreased expression levels of BACE1 and APP and increased expression of MMP2 and MMP9 were found by cellular experiments, and FA may be a potential herbal component for the treatment of Alzheimer’s disease." (PMID 39372201, 2024). "Unfortunately, some of the induced proteins, including beta-site amyloid precursor protein cleaving enzyme-1 (BACE1), may increase the production of pathological proteins in neurodegenerative diseases, such as β-amyloid precipitation in Alzheimer’s disease (AD)." (PMID 36910151, 2023). "Ng, BACE1 and Ng/BACE1 CSF levels are consistent phenotypes across A/T/N-stages and may present different Alzheimer’s disease subgroups rather than reflecting disease progression." (PMID 36262371, 2022). "Thus, longitudinal data does not show BACE1, Ng or Ng/BACE1 changes coinciding with stage-wise Alzheimer’s disease progression but gives evidence of lasting differences between cases over the observation period, also with increasing core pathologies." (PMID 36262371, 2022). "Besides finding the microRNAs that could regulate the critical nodes such as APP, BACE1, CD4, DCN, IL8 and PSEN1, we searched to uncover additional regulatory mechanisms of Alzheimer’s disease genes." (PMID 26784894, 2016). "Moreover, we show that both Syt-1 and Syt-9 increase Aβ levels likely via BACE1-mediated APP processing and thus may play an important role in Alzheimer’s disease pathology." (PMID 26202512, 2015). "The existence of Aβ-like fragments of mEpCAM is described for the first time in the present study and might add up to a potential role for this part of the protein, possibly in conjunction with the cleavage through BACE1, as was extensively described for APP in Alzheimer’s disease." (PMID 24009667, 2013). "The amino acid aggregates of Aβ peptides forming the major component of plaques characteristic of Alzheimer's Disease (AD) result from N-terminal cleavage of the amyloid precursor protein (APP) mediated by an aspartyl protease referred to as Beta-site APP Cleaving Enzyme 1 (BACE1)." (PMID 24381583, 2013). "Since the identification of β-secretase (memapsin 2, BACE1) more than a decade ago, significant research effort from many laboratories around the world has been directed towards the development of inhibitor drugs against this β-secretase as a potential treatment of Alzheimer's disease (AD)." (PMID 21248377, 2011). "Recently, there has been increasing interest in the development of small, non-peptide inhibitors of the β-amyloid cleaving enzyme 1 (BACE-1, β-secretase), following the suggestion that this enzyme may be involved in the pathogenesis of Alzheimer’s Disease (AD)." (PMID 32927879, 2020). "In Alzheimer's disease, BBR could be effective in decreasing the generation of the beta-amyloid (Aβ) peptide by APP processing in H4 human neuroglioma cells, and in inhibiting the activity of beta-site APP cleaving enzyme-1 (BACE-1) in a rabbit model of Alzheimer's disease." (PMID 32855766, 2020). "Also, it has been demonstrated that ciRS-7 can repress Alzheimer’s disease (AD) development by suppressing NF-κB protein synthesis and inducing its cytoplasmic localization, promoting UCHL1 expression and UCHL1-induced amyloid precursor protein (APP) and BACE1 ubiquitination and degradation." (PMID 30161026, 2018). "However, over the last decade, it has become clear that BACE1 not only cleaves APP but also has a number of other proteolytic substrates which are not known to be involved in the pathogenesis of Alzheimer’s disease but rather have other roles in the central nervous system." (PMID 27456313, 2016).
Alzheimer disease (continued). "In comparison, asperterpene A showed similar activity to LY2811376, the first orally bioavailable non-peptide BACE1 inhibitor, showing an IC50 range of 239 nM to 249 nM and an EC50 of 300 nM in the context of Alzheimer’s disease at 3xTg-mice." (PMID 39996817, 2025). "BACE1 is involved in two different pathways that produce amyloid-beta through reverse cholesterol transport, and its role in APP cleavage offers potential to treat Alzheimer’s disease early on rather than treating the disease later in its progression." (PMID 37444065, 2023). "BACE1 competes with BACE2 over APP substrate, but their enzymatic activity generates different type of products in which the product of BACE1 but not BACE2 leads to Alzheimer's disease." (PMID 25254246, 2014).
Cognitive impairment (133 papers, 2007 to 2026). Abnormal cognition is characterized by deficits in thinking, reasoning, or remembering. "Another study also reveals a significant trend towards increased risk for mild cognitive impairment (MCI) with high plasma BACE1 level and insulin resistance in type 2 DM patients." (PMID 41446639, 2025). "Animal model studies have been extensively performed to explore the mechanism of BACE1 as a risk for promoting cognitive impairment in DM patients through β-amyloidogenesis and insulin resistance." (PMID 41446639, 2025). "Subsequently, we performed Western blots to assess the protein level of amyloid precursor protein (APP) and β-site APP cleaving enzyme-1 (BACE1) in the hippocampus, a phenomenon associated with cognitive impairment." (PMID 39200168, 2024). "During the last 20 years, several human in vivo studies have shown a good diagnostic performance of cerebrospinal fluid (CSF) BACE1 activity/levels in discriminating AD patients from mild cognitive impairment (MCI) subjects and healthy controls." (PMID 39125924, 2024). "These researchers showed that an Nrf2 deficiency increases BACE1 expression and exacerbates Aβ plaque loads and cognitive deficits in 5XFAD mice." (PMID 37408220, 2023). "Our subgroup analysis found an interesting result that in AD patients with only mild cognitive impairment, BACE1 inhibitors were associated with an exacerbation of cognitive decline in even more secondary efficacy outcomes and safety concerns remain." (PMID 38020763, 2023). "Dystrophic neurites contain high levels of LAMP1 and BACE1, and significantly contribute to extracellular plaque deposition and axonal dystrophy, resulting in synaptic loss, neurodegeneration, and cognitive deficits." (PMID 35987691, 2022). "Preclinical studies have associated BACE1-inhibition-induced cognitive deficits with decreased dendritic spine density." (PMID 35936777, 2022). "First, the study was cross-sectional, thereby precluding our ability to establish any cause/effect relationship between BACE1 and cognitive impairment/dementia." (PMID 32917964, 2020). "It was reported that excessive p-eIF2α caused cognitive defects, increased β-secretase 1 (BACE1), and promoted amyloidogenesis." (PMID 28561773, 2017). "APP transgenic mouse models of AD that are devoid of BACE1 expression via BACE1 gene knockout (BACE1−/− mice) fail to generate Aβ and lack the amyloid plaques and cognitive impairments found in APP transgenic mice that express both BACE1 alleles." (PMID 25567526, 2015). "Although EpoR76E treatment did not restore all normal functions in 5xFAD mice, it protected against cognitive impairment, presumably by promoting the maintenance of synaptic clefts and reducing Aβ-associated toxicity, possibly by reducing expression of the β-secretase BACE1." (PMID 40321747, 2025). "Both clinical and nonclinical studies presented a range of adverse effects upon the administration of BACE-1 inhibitors such as retinal toxicity in animals, hepatotoxicity in humans, cognitive impairment, weight loss, sleep disturbances, anxiety, and suicidal ideation." (PMID 35956919, 2022). "As miRNAs predominantly promote degradation, destabilization, and repression of mRNA, a reduction of hsa-miR-107 might lead to an increased expression of BACE1, thereby initiating the cascade that increases the risk for cognitive deficits." (PMID 35884866, 2022). "Studies conducted on APP/PS1 mice, a model of AD, revealed that FoA deficiency intensify Aβ generation improving APP and beta-site amyloid precursor protein cleaving enzyme 1 (BACE1) expression, suggesting that folic acid deficiency exacerbates cognitive impairment." (PMID 35213966, 2022). "ELS upregulates Aβ levels and BACE1 expression, which may underlie cognitive deficits such as reversal learning, and may thus be a risk factor for AD in vulnerable individuals." (PMID 29491368, 2018).
Cognitive impairment (continued). "If administered at a very early disease stage prior to the substantial accumulation of the Aβ-protein and loss of synapses, therapeutic intervention with BACE1-inhibition may well arrest the pathology progression and spare the patient from severe cognitive impairment." (PMID 35936777, 2022). "The present study examined the regulatory effects of repeated EA therapy on BACE1 expression and its associated substrates, to determine whether EA could effectively alleviate cognitive impairments of APP/PS1 mice and further elucidate the mechanism underlying the antidementia response of EA." (PMID 31223308, 2019). "Therefore, BACE1 is classified as a hallmark of early cognitive impairment." (PMID 28851397, 2017). "Another study found that platelet BACE1 expression is increased by 24% in patients with mild cognitive impairment (MCI) compared to healthy controls suggesting that platelet BACE1 is augmented in early AD." (PMID 39757022, 2025). "RNA interference-based reversal of increased BACE1 to control levels in the brain blocks DM-associated Aβ/β-CTF elevations and cognitive deficits in the STZ rat model." (PMID 41446639, 2025). "Regarding neuroinflammation, STZ model group showed raised NF-κB, IL-6, and BACE-1 to add explanation of cognitive impairment occurred in this study." (PMID 40381124, 2025). "Studies have shown that the activity of BACE1 is significantly elevated in the brain tissue and cerebrospinal fluid (CSF) of patients suffering from mild cognitive impairment and sporadic Alzheimer’s disease." (PMID 40291844, 2025). "In accordance with previous studies, administration of LPS showed an elevated BACE1 activity and increased Aβ level in the rats’ hippocampi, which is considered a precursor to the cognitive impairment and spatial memory dysfunction seen in this recent study." (PMID 37712973, 2024). "In conclusion, our research findings revealed that Trolox exhibited multidimensional effects by reducing Aβ, p-tau, and BACE1 expressions both in cortical and hippocampal regions and mitigating memory, learning, and cognitive impairments in AD-induced mice." (PMID 39355174, 2024). "In AD and mild cognitive impairment subjects, BACE1 activity is increased in brain/cerebrospinal fluid, and plasma levels appear to reflect those in the brain." (PMID 39125924, 2024). "Carotenoids exert neuroprotective effects through different mechanisms: fucoxanthin inhibits BACE1, reducing Aβ plaque aggregation; astaxanthin provides general neuroprotection, and lutein specifically mitigates Aβ-induced cognitive deficits." (PMID 39274904, 2024). "Studies have shown that genetic deletion or inhibition of BACE1 in animal models can significantly reduce beta-amyloid levels and ameliorate AD-related cognitive impairments." (PMID 37759801, 2023). "Thus, BACE1-inhibitor intervention might be ideally started before to the accumulation of the Aβ-protein, synaptic loss as well as the onset of potentially irreversible cognitive deficits in order to achieve a positive outcome on cognition." (PMID 35936777, 2022). "Several lines of evidence have shown that Sirt2 inhibitor (AGK-2 and AK-7) injection in AD-like mouse models decreased Aβ generation by reducing BACE1 levels, thus leading to an amelioration of cognitive impairment." (PMID 35701718, 2022). "It inhibited the expression of BACE1 and BACE1-AS by binding to ARE in mouse promoters, decreasing the formation of BACE1, BACE1-AS transcripts, and the formation of Aβ, and specifically mediated cognitive impairment in animal models of AD." (PMID 35656102, 2022). "Intriguingly, expression of BACE1 protein was significantly up-regulated *(P < 0.05) only in the minor cognitive impaired group and in patients diagnosed with HIV with a diagnosis of AD, compared to uninfected individuals." (PMID 32453744, 2020). "Expression of miR-107 and BACE1 mRNA correlated with alterations in brain pathology in individuals with mild cognitive impairment." (PMID 33013313, 2020).